EIF3H (eukaryotic translation initiation factor 3 subunit H)
Diseases named in the same sentence as EIF3H in open-access papers (continued):
Sharing a sentence is not in itself a finding about the gene and the disease.
tumor (continued). "Correspondingly, our findings are the first to reveal that EIF3H inhibits ferroptosis by interacting with OGT, thereby accelerating HCC cell growth and tumor progression." (PMID 37559097, 2023). "Difference is found in the expression of EIF3A, EIF3B, EIF3D, EIF3F, EIF3H, EIF3J, and EIF3M in different tumor stages." (PMID 36051357, 2022). "The eukaryotic translation initiation factors, namely, EIF1, EIF3E, EIF3H, EIF4G2, EIF5, and EIF6, were all upregulated in the brain metastasis-derived tumor cells." (PMID 33170151, 2020). "Our study reveals a critical EIF3H-Snail signaling axis in tumor aggressiveness in ESCC and provides EIF3H as a promising biomarker for ESCC treatment." (PMID 32867821, 2020). "A univariate analysis revealed that the gender, tumor size, Edmondson grade, micro-vascular invasion, macro-vascular invasion, pathological satellite, encapsulation, TNM stage, BCLC stage, AFP and EIF3H expression were significantly correlated with RFS or OS." (PMID 27340783, 2016). "EIF3H mRNA expression was measured in HCC tissue samples and paired non-tumor samples (N=60) and results were validated in another dataset of 215 HCC patients." (PMID 27340783, 2016). "Data from 60 paired HCC tumor samples and para-cancerous normal tissue samples confirmed that EIF3H mRNA was significantly differentially expressed (Fold change=3.654, P=0.002) in HCC tumor tissue." (PMID 27340783, 2016). "Data show that EIF3H was differentially expressed between HCC and non-tumor samples (Fold change=3.654, P=0.002)." (PMID 27340783, 2016). "In this study, we quantified EIF3H mRNA and protein in HCC tumor tissue, para-cancerous normal tissue, and various HCC cell lines." (PMID 27340783, 2016). "To investigate the influence on tumor progression through the YAP O‐GlcNAcylation and subsequently EIF3H guided stabilization, we established EIF3H knockdown (shEIF3H) in 4T1 and EIF3H knockout (EIF3H KO) in MDA‐MB‐231, using cells with an empty vector as the control group." (PMID 39868848, 2025). "Therefore, our study demonstrates a critical EIF3H-Snail signaling axis in EMT process and tumor metastasis in ESCC." (PMID 32867821, 2020). "Immunohistochemical analysis agreed with blot data, indicating that EIF3H protein was upregulated in tumor tissues compared to non-tumor tissue." (PMID 27340783, 2016). "Most importantly, we first measured differential expression of EIF3H in HCC tumor samples and non-tumorous normal tissue samples and we associated elevated EIF3H expression and clinical outcomes in early stage HCC patients." (PMID 27340783, 2016). "The increased expression of anti-apoptotic genes, including EIF3H, RFFL and HDAC2, may favorably assist uncontrolled cell growth and proliferation to enhance tumor growth in patients with HCC-R." (PMID 24377043, 2013). "In the pursuit of innovative therapeutic strategies, by pharmacologically targeting the HBP/EIF3H/YAP axis, we demonstrate the feasibility of reactivating the degradation process of YAP, thereby enhancing the potency of chemotherapeutic agents and impeding tumor progression." (PMID 39868848, 2025). "Besides, nine eIF3 subunits beyond eIF3D were found aberrantly expressed in LUAD tissues and in which the expression levels of five subunits (eIF3B, eIF3C, eIF3E, eIF3H, and eIF3J) increased in LUAD patients with high tumour stage, implicating their roles in the maintenance or progression of LUAD." (PMID 31885740, 2019). "The other four genes (CPS1, COL12A1, EIF3H, and NBR1) were not upregulated in the tumour region of MSSCC." (PMID 21847129, 2011).
infection (1 paper, 2016). The state of being infected such as from the introduction of a foreign agent such as serum, vaccine, antigenic substance or organism. "Western blot, performed 3 days after infection, confirmed a significant decrease in EIF3H protein expression in EIF3H-siRNA infected cells, compared to control scramble siRNA infected cells." (PMID 27340783, 2016). "Western blot performed 3 days after infection confirmed significant decreases in EIF3H protein expression in EIF3H-siRNA infected cells, compared to control scramble siRNA-infected cells." (PMID 27340783, 2016). "EIF3H-siRNA infection effectively reduced expression of EIF3H in both cell lines as confirmed by qRT-PCR and Western blot." (PMID 27340783, 2016). "Using lentiviral-mediated siRNA to inhibit EIF3H expression in SMMC-7721 and LM3 HCC cell lines, we noted that more than 90% of cells remained (MOI 10) on day 5 after infection." (PMID 27340783, 2016).
EIF3H also shares sentences with these, for which no sentence is quoted: Acute hepatitis (1 paper); colorectal adenoma (1); ductal carcinoma (1); gastric cancer (1); Hepatic steatosis (1); Langer-Giedion syndrome (1); liver diseases (1); lobular carcinomas (1); lymphoma (1); mastitis (1); metabolic disorders (1); metastatic prostate carcinoma (1); neurodegenerative disease (1); otosclerosis (1); ovarian carcinoma (1); prostate tumours (1); testicular cancer (1).